COL2A1 (collagen type II alpha 1 chain)
Diseases named in the same sentence as COL2A1 in open-access papers (continued):
Sharing a sentence is not in itself a finding about the gene and the disease.
Stickler syndrome (continued). "We examined 40 Japanese patients with Stickler syndrome from 23 families to determine whether they had mutations in the COL2A1 gene." (PMID 27408751, 2016). "As pathogenic variants in this region of COL2A1 can result in type 1 Stickler syndrome, it has been suggested that haploinsufficiency of BMP4 may affect these interactions with type II collagen, disrupting the development of vitreous and cartilage, producing a similar phenotype." (PMID 35741851, 2022). "During development, COL2A1 is expressed in cranial neural crest cells that ultimately form the mandible, maxilla, and the bones of the inner ear, which accounts for the additional micrognathia, cleft palate, and hearing loss that is also observed in Stickler syndrome." (PMID 36278547, 2022). "COL2A1 and COL11A1 were responsible for Stickler syndrome (15%, 6/40) and VCAN was associated with Wagner syndrome (5.0%, 2/40)." (PMID 40270540, 2025). "The other detected genes in this study, such as those related to Stickler syndrome (COL2A1 and COL11A1) or Marfan syndrome (FBN1), which have been proposed to modulate ocular growth through axial mechanism." (PMID 38243264, 2024). "STL1 is caused by a heterozygous mutation in COL2A1 and confirms the diagnosis in the vast majority of Stickler syndrome cases." (PMID 36140739, 2022). "Genetic mutations of COL2A1 and COL11A1 seen in Stickler Syndrome affect the incidence of mandibular distraction osteogenesis." (PMID 35198553, 2022). "A membranous type of congenital vitreous anomaly is mainly seen in type 1 Stickler syndrome (STL1, COL2A1), whereas a beaded vitreous anomaly is often associated with type 2 Stickler syndrome (STL2, COL11A1)." (PMID 36140739, 2022). "On the basis of the vitreous phenotype, fluorescent sequencing of COL2A1 was initiated and confirmed a heterozygous base change in exon 42 resulting in premature termination codon and haploinsufficiency typical of type 1 Stickler syndrome." (PMID 34611315, 2022). "Stickler syndrome is a collagenopathy that is typically COL2A1‐related (autosomal dominant) and less commonly related to other collagen gene mutations." (PMID 33951325, 2021). "Globally, the most common form of Stickler syndrome is autosomal dominant COL2A1‐related Sticker syndrome Type 1, which accounts for 80%–90% of cases." (PMID 33951325, 2021). "Compared with SEDC, another subtype of COL2A1-related diseases type I of Stickler syndrome (STL1) had a much higher incidence of SNHL, from 50 to 75%." (PMID 34182999, 2021). "To date, mutations in seven genes (COL2A1, COL11A1, COL11A2, COL9A1, COL9A2, COL9A3, and LOXL3) have been reported to cause Stickler syndrome." (PMID 32756486, 2020). "To date, multiple mutations in the collagen-encoding genes COL2A1, COL11A1, COL11A2, COL9A1, COL9A2, and COL9A3 have been associated with six genetically distinct types of Stickler syndrome." (PMID 28335520, 2017). "The Stickler syndrome-related collagens, Col2a1, Col11a1, and Col11a2, are important components of both the cochlear TM and cartilage." (PMID 22567353, 2011). "Ocular features of Stickler's syndrome and other COL2A1 genetic disorders (reviewed) commonly include myopia, vitreoretinal degeneration, retinal thinning, retinal detachment, cataract, and glaucoma." (PMID 18523590, 2008). "Among these are collagen, type XVIII, alpha 1 (COL18A1) for Knobloch and collagen, type II, alpha 1 (COL2A1) for Stickler syndrome." (PMID 17653045, 2007). "These genes are associated with recognizable syndromes such as (acampomelic) campomelic dysplasia (SOX9), cerebro‐costo‐mandibular syndrome (SNRPB), SATB2‐associated syndrome (Glass syndrome, SATB2), Catel‐Manzke syndrome (TGDS), TARP syndrome (RBM10), and Stickler syndrome (COL2A1, COL11A1)." (PMID 41077824, 2026). "Notably, the most common pathogenic genes in high myopia cases with retinal detachment were those related to Stickler syndrome, particularly COL2A1 (10.0%, 4/40) and COL11A1 (5.0%, 2/40)." (PMID 40270540, 2025).
Stickler syndrome (continued). "A recent meta-analysis of 400 eyes of 225 patients with COL2A1- or COL11A1-related Stickler syndrome reported an RD rate of 6.6% (6.3 years mean follow-up duration) in patients who had prophylactic laser retinopexy compared to 36.0% (4.0 years mean follow-up duration) in patients without laser." (PMID 41153400, 2025). "In this study, we identified a novel mutation (a non-exon 2 mutation) in the COL2A1 gene in a family diagnosed with predominantly ocular Stickler syndrome." (PMID 41050055, 2025). "Although individual report had linked a deep intronic COL2A1 mutation to a family with early-onset high myopia/ocular-only Stickler syndrome, WES remains the primary method for the early diagnosis of predominantly ocular Stickler syndrome." (PMID 41050055, 2025). "RRD is related to pathological mechanical changes in the vitreoretinal interface (e.g., posterior vitreous detachment, PVD; lattice degeneration, 30–46% of RRD); thus, genetic variants in collagen genes (e.g., COL2A1, COL11A1, COL18A1) are logically implicated in Stickler syndrome." (PMID 41465105, 2025). "The molecular basis for these phenotypic differences remains unknown and demonstrates the need for deep phenotyping in patients with Stickler syndrome to correlate COL2A1 gene function and expression with ocular and systemic findings." (PMID 37107605, 2023). "The ocular-only phenotype of Stickler syndrome is not wholly confined to pathogenic variants of exon 2 of COL2A1." (PMID 35741851, 2022). "On the basis of the vitreous phenotype fluorescent sequencing of COL2A1 was initiated and confirmed a heterozygous deletion of two nucleotides in exon 52 of the COL2A1 gene resulting in a frameshift and haploinsufficiency, typical of type 1 Stickler syndrome." (PMID 34611315, 2022). "Previous research has identified collagen gene expression, specifically col2a1 and col11a1a in the developing zebrafish ear, consistent with reported craniofacial and hearing defects that occur in fibrochondrogenesis, as well as Stickler’s syndrome patients." (PMID 36278545, 2022). "However, COL11A1‐related disease accounts for only 10–20% of Stickler syndrome worldwide while COL2A1‐related disease accounts for 80–90% of cases." (PMID 33951325, 2021). "Mutations in the COL2A1, COL11A1, and COL11A2 procollagen genes cause Stickler syndrome." (PMID 28841907, 2017). "Indeed, mutations in COL2A1, COL11A1, COL11A2, COL9A1, COL9A2, and COL9A3 have been associated with Stickler syndrome and early-onset OA." (PMID 28335520, 2017). "We next suspected Stickler syndrome and conducted COL2A1 genetic analysis." (PMID 28841907, 2017). "These alterations included vitreous changes similar to those seen in patients with Stickler syndrome, which included reduced immunostaining of type II collagen in the vitreous and retina, in addition to reduced density of vitreous filaments in COL2A1+/− mutant mice." (PMID 23592912, 2013). "In patients with Stickler syndrome, the majority of mutations in the COL2A1 gene that lead to a premature termination codon trigger the nonsense-mediated mRNA decay (NMD) mechanism, ultimately causing haploinsufficiency of the COL2A1 gene and thereby affecting collagen synthesis." (PMID 41050055, 2025). "On the basis of the vitreous phenotype a diagnosis of Type 1 Stickler syndrome was made and a whole gene sequence analysis including all introns of COL2A1 was carried out which identified a deep intronic (c.2194-101 G > T in intron 33) sequence variant of unknown clinical significance." (PMID 34611315, 2022). "Similarly, mutations in the collagen-α chain genes, COL2A1, COL9A2, COL11A1, and COL11A2, have been associated with different forms of Stickler syndrome (OMIM#108300, #614284, #604841, and #184840, respectively), a clinically variable condition that includes cleft palate." (PMID 28106045, 2017).
Stickler syndrome (continued). "This multi-center study was able to broaden the genetic variation spectrum of COL2A1 and COL11A1 genes in Korean patients with Stickler syndrome." (PMID 34680973, 2021). "In COL9A1-related autosomal recessive Stickler syndrome, the vitreous does not phenocopy the classic type 1 Stickler syndrome (COL2A1; membranous vitreous) or type 2 Stickler syndrome (COL11A1; beaded vitreous) patterns." (PMID 41153400, 2025). "Exome sequencing identified 21 potential pathogenic variants of 13 genes in 20 of 75 (26.7%) probands, including genes for Stickler syndrome (COL11A1 and COL2A1; 6/20), FEVR (FZD4, LRP5, and TSPAN12; 5/20), and others (FBN1, GPR179, ZEB2, PAX6, GPR143, OPN1LW, FRMD7, and CACNA1F; 9/20)." (PMID 38243264, 2024). "These systemic syndromes can be caused by a series of genes, including NYX, CACNA1F, GRM6, and LRIT3, responsible for congenital stationary night blindness (CSNB); COL2A1, COL11A1, COL9A1, and COL9A2, responsible for Stickler syndrome; and FBN1, responsible for Marfan syndrome." (PMID 36980859, 2023). "Genetic clarification was not sought in this study, although the authors presumed that “most, if not all” subjects had genetic abnormalities in COL2A1 (type 1 Stickler Syndrome)." (PMID 32901364, 2021). "Consistent with previous studies, retinal detachment developed in 58.2% of patients with COL2A1-related Stickler syndrome who did not undergo laser prophylaxis, compared to 37.5% of patients with COL11A1-related Stickler syndrome." (PMID 41153400, 2025).
osteoarthritis (53 papers, 2009 to 2026). A noninflammatory degenerative joint disease occurring chiefly in older persons, characterized by degeneration of the articular cartilage, hypertrophy of bone at the margins and changes in the synovial membrane. "There is a gradual decrease in the mRNA levels of Col2a1, Acan and Sox9 and an increase in Runx2 associated with osteoarthritis." (PMID 39600948, 2024). "The COL2A1 gene mutations result in several types of chondrodysplasia, leading to premature osteoarthritis." (PMID 34572492, 2021). "In contrast to our findings, cartilage‐specific deletion of PPARγ using Col2a1‐Cre caused severe osteoarthritis in 14‐month‐old mice, associated with synovial inflammation and expression of catabolic factors." (PMID 33048436, 2020). "For instance, the human ortholog of Acan, Col2a1, and Col11a1 are linked to spondyloepiphyseal dysplasia, osteoarthritis, disc degeneration, and susceptibility to lumbar disc herniation." (PMID 28011632, 2017). "DOT1L inhibition enhanced the osteoarthritis-like gene expression changes, for example, augmenting loss of COL2A1 and gain of COL1A1 expression." (PMID 28627522, 2017). "Heterozgyous spondyloepiphyseal dysplasia congenita (sedc/+) mice expressing a missense mutation in col2a1 exhibit a normal skeletal morphology but early-onset osteoarthritis (OA)." (PMID 23939426, 2013). "COL2A1 was reported to be linked to nodal osteoarthritis and it was highly significantly (P < 0.01) associated with front leg pastern and front uneven toes." (PMID 19284518, 2009). "Notably, the ratio of COL2A1 (which encodes type II collagen) to COL1A1 expression drops dramatically as osteoarthritis progresses, indicating a shift towards a more fibroblastic phenotype in chondrocytes." (PMID 41019141, 2025). "Children with ACAN mutations may develop early-onset joint pain or osteoarthritis, while variants in COL2A1 or FLNB may lead to orthopedic complications." (PMID 40723048, 2025). "Additionally, Granch and colleagues have demonstrated that polymorphisms in the COL2A1 gene are also associated with osteoarthritis (OA) secondary to DDH." (PMID 39902299, 2024). "The increased expression of COL1A1, along with COL2A1, is thought to reflect the metabolic activation of chondrocytes in response to the osteoarthritis process." (PMID 41019141, 2025). "The p.Arg275Cys mutation in the COL2A1 gene has been previously reported to manifest as spondyloepiphyseal dysplasia congenita (SEDC), spondyloarthritis, early-onset osteoarthritis (EO-OA), and Czech dysplasia." (PMID 39902299, 2024). "Meanwhile, we examined the osteoarthritis markers collagen type II (COL2A1) and matrix metalloproteinase 13 (MMP13)." (PMID 37620972, 2023). "COL2A1 and ACAN genes are directly associated with the Osteoarthritis pathway, which are represented by the solid lines, while COL1 and SOX6 are not, which are represented by the dotted lines." (PMID 34970658, 2019). "This in turn accelerates hypertrophy, promoting further depletion of COL2A1 and ultimately leading to full-blown osteoarthritis." (PMID 30854241, 2019). "In particular, centromere protein-C, insulin growth factor binding protein 2, and LDH have not been previously linked to an imbalance of damage and repair in osteoarthritis, whereas, TNC and COL2A1 have already been reported." (PMID 23773399, 2013). "A recently developed mouse model detected reduced Acan and Col2a1 in mice with osteoarthritis." (PMID 39600948, 2024). "In the present study, chondrocytes stimulated with IL-1β exhibited downregulation of COL2A1 and upregulation of MMP13, Prg4, Sulf1, Adam10, and Fstl1, supporting that enhanced inflammation is a critical mechanism underlying the progression of osteoarthritis." (PMID 37525533, 2023).
osteoarthritis (continued). "Meanwhile, Runx2 conditional knockout mice showed biphasic phenotypes: heterozygous knockout inhibited osteoarthritis and decreased matrix metallopeptidase 13 (Mmp13) expression, while homozygous knockout of Runx2 accelerated osteoarthritis and reduced type II collagen (Col2a1) expression." (PMID 36261443, 2022). "The changes in expression of the DEGs listed in the osteoarthritis pathway included strong down-regulation of cartilage matrix molecules (COL2A1, MATN3, and ACAN) and up-regulation of matrix proteases (ADAMTS5 and MMP13) and apoptosis-related molecules (CASP4)." (PMID 32294904, 2020). "Our study reveals novel mechanisms for the inhibition of chondrocyte hypertrophy by COL2A1 and suggests that the degradation and decrease in COL2A1 might initiate and promote osteoarthritis progression." (PMID 30854241, 2019). "Therefore, the use of the Cbfbf/f;Col2a1-CreERT mouse mutant strain was instrumental in expanding our understanding of Cbfβ’s multifaceted role in osteoarthritis, highlighting its importance not only in mature cartilage but also in the early stages of cartilage formation and differentiation." (PMID 38805545, 2024). "Alteration of the osteoarthritis pathway due to RARγ agonist treatment was associated with the up-regulation of catabolic genes (ADAMTS5, HES1, and MMP13), inhibition of cartilage matrix anabolic genes (COL2A1, ACAN, and SOX9) and the up-regulation of death genes (CASP4)." (PMID 32294904, 2020). "The analysis revealed a notable upregulation of key osteoarthritis markers, such as COL10A1, MMP13, and SPP1, along with downregulating chondrogenic markers, including ACAN, COL1A2, COL2A1, and SOX9." (PMID 39337501, 2024). "MMPs are responsible for the degradation of the extracellular matrix protein COL2A1, in which MMP13 is a dominant player in the progression of osteoarthritis." (PMID 37525533, 2023). "Induction of an osteoarthritis-like phenotype in the ATDC5 chondrocytes was confirmed by a significant upregulation of il6, mmp13, and colx10a1 and a decrease in col2a1 and acan expression following treatment with IL-1β." (PMID 36814717, 2023). "Inhibition of JAK rescues chondrogenic differentiation in osteoarthritis-like conditions, and IFN-γ has been demonstrated to inhibit transcription of the COL2A1 gene in mature chondrocytes." (PMID 30718282, 2019). "This prominent microRNA can target osteoarthritis (OA)-related mRNAs, ADAMTS-5, MMP13, COl2a1, and ACAN in human articular chondrocytes." (PMID 31847882, 2019). "To address this issue, we focused our attention on the expression levels of molecules that were previously shown to be modulated during the onset of IVD degeneration or osteoarthritis (COL1A1, COL2A1, AGC1, BMP2, MMP13, MGP and P21)." (PMID 21726455, 2011). "In addition, Deng and collaborators demonstrated that YAP-specific overexpression in chondrocytes, in transgenic Col2a1-YAP mice or by Mst1/2 deletion under Cre-recombinase Col2a1, protected articular cartilage against osteoarthritis." (PMID 35059398, 2021). "In our current study, the Col2a1-CreERT system allowed us to investigate Cbfβ’s role not only in mature chondrocytes but also in early chondroprogenitor cells, offering a comprehensive view of Cbfβ’s involvement in cartilage in osteoarthritis." (PMID 38805545, 2024). "Its overexpression induces suppression of SMAD3, resulting in inhibition of cell proliferation, migration, and invasion in osteosarcoma cells, and in downregulation of COL2A1 and Aggrecan and upregulation of ADAMTS in chondrocytes, which may be involved in the development of osteoarthritis." (PMID 35401675, 2022). "Expression of COL2A1 and Acan mRNA rather enhances in lower concentration of H2O2 in both primary chondrocytes and RCS cells, may indicating that mild damage of chondrocytes by oxidative stress rather induces synthesis of cartilaginous matrices observed in early stage of osteoarthritis." (PMID 33066270, 2020).